RCVRN (recoverin)
Diseases named in the same sentence as RCVRN in open-access papers (continued):
Sharing a sentence is not in itself a finding about the gene and the disease.
myelitis (2 papers, 2025). An inflammatory process affecting the spinal cord. "We present a case of severe myelitis in a 76-year-old man with positive anti-recoverin antibodies that occurred one week after RSVPreF3 vaccination against respiratory syncytial virus (RSV)." (PMID 40917683, 2025). "PNS can emerge with tumor recurrence, and cases have been reported where PNS phenotype and anti-neuronal antibodies differed between initial diagnosis and recurrence (e.g., anti-recoverin retinopathy at diagnosis vs. anti-CV2/CRMP5 myelitis at recurrence)." (PMID 41542009, 2025). "Although there is a limitation regarding the causality of anti-recoverin antibodies, RSV vaccination, and myelitis, this association has not been previously reported." (PMID 40917683, 2025).
paraneoplastic neurological syndrome (2 papers, 1996 to 2022). "Cancer-associated retinopathy is usually caused by recoverin, in which aberrant expression can activate a host immune response followed by development of a paraneoplastic neurological syndrome." (PMID 35646664, 2022).
retinoblastoma (2 papers, 2018 to 2021). A malignant tumor that originates in the nuclear layer of the retina. "Retinoblastoma cells express not only NCS-1 but also recoverin, both of which form disulfide aggregates and may collectively affect proteasome capacity." (PMID 34830487, 2021).
anterior uveitis (1 paper, 2021). Inflammation of the iris and anterior chamber of the eye. "Although not significant, some tendencies can be observed; e.g., autoreactivity against HSP70 and recoverin was more frequent among congenital cases with panuveitis, anti-recoverin reaction was prevalent among cases of acquired infection and with anterior uveitis." (PMID 34054794, 2021).
brain tumors (1 paper, 2024). "In cohort B, most common diagnoses were neurodegenerative disorders in 9/39 (23.1%), brain tumors in 6/39 (15.4%) while most common detected antibodies were anti–titin (N10), anti-recoverin (N11), anti-Yo (N8) and all were detected in serum only." (PMID 38438516, 2024).
cerebral toxoplasmosis (1 paper, 2021). Infections of the brain caused by the protozoan toxoplasma gondii that primarily arise in individuals with immunologic deficiency syndromes (see also aids-related opportunistic infections). "The frequency of anti-HSP70 and anti-recoverin antibodies was higher in patients with congenital infection and specifically in those with some type of CNS manifestation, even in patients with cerebral toxoplasmosis without ocular infection." (PMID 34054794, 2021). "The presence of anti-recoverin antibodies in individuals with congenital cerebral toxoplasmosis without ocular pathology may suggest that recoverin epitopes may be shared with another CNS endogenous antigen, resulting in cross-reactivity between the two." (PMID 34054794, 2021).
colonic adenoma (1 paper, 2014). "Surprisingly, colonic adenoma excised from the patient was potently immunopositive for recoverin, leading us to advocate “benign tumor-associated retinopathy (BAR)”." (PMID 24428923, 2014).
congenital toxoplasmosis (1 paper, 2021). Toxoplasma infection that is present from birth. "Nevertheless, some results deserve attention: except for the cases with congenital toxoplasmosis and isolated OT, all groups or subgroups presented a larger proportion of positives against recoverin than against HSP70." (PMID 34054794, 2021).
Down syndrome (1 paper, 2019). "These images show comparisons between Down syndrome and normal fetal retinas for photoreceptors (RCVRN, OTX2) and bipolar cells (VSX2) amacrine cells (ELAVL3/4) and synapses (VGLUT/SLC17A7)." (PMID 30842553, 2019). "If there was accelerated development in the Down syndrome retinas, we would expect to see a greater number of VSX2+ bipolar cells, more mature photoreceptors (RCVRN) and an increase in VGLUT/SLC17A7 labeling, but we do not see these changes." (PMID 30842553, 2019).
Encephalopathy (1 paper, 2024). Encephalopathy is a term that means brain disease, damage, or malfunction. "Retinopathy, small fiber neuropathy (SFN), and encephalopathy associated with recoverin antibodies have not been previously reported as side effects of BNT162b2 vaccination in a patient with HLA-B27-associated spondylarthritis." (PMID 39280509, 2024).
focal epilepsy (1 paper, 2019). A seizure caused by a localized disorder. "Antibodies were detected against GAD in 1 (3%), APL in 1 (3%), NMDA-R in 2 (6.1%), CV2 in 1 (3.0%), Tr in 1 (3.0%), GABA in 11 (33.3%), recoverin in 1 (3.0%), dsDNA in 1 (3.0%) of our patients with focal epilepsy." (PMID 31316731, 2019).
glioma (1 paper, 2022). A benign or malignant brain and spinal cord tumor that arises from glial cells (astrocytes, oligodendrocytes, ependymal cells). "As the recoverin is aberrantly generated and a potential cancer retina antigen is released into the glioma microenvironment, it is likely that the tumor microenvironment is attracting APCs and DCs." (PMID 35646664, 2022).
gynecologic cancers (1 paper, 2024). "Patients with CAR express various antibodies, notably anti-recoverin (23 kD) targeting photoreceptor cells, linked primarily to small-cell lung and gynecologic cancers." (PMID 38961469, 2024).
Hydrocephalus (1 paper, 2021). Hydrocephalus is an active distension of the ventricular system of the brain resulting from inadequate passage of CSF from its point of production within the cerebral ventricles to its point of absorption into the systemic circulation. "Within the group with neuro-ophthalmic toxoplasmosis an unexpected result was observed: the highest frequency of anti-HSP70 and anti-recoverin antibodies was in patients without hydrocephalus, without cerebral calcifications and with the least number of ocular complications." (PMID 34054794, 2021).
ischemia (1 paper, 2013). A hypoperfusion of the BLOOD through an organ or tissue caused by a PATHOLOGIC CONSTRICTION or obstruction of its BLOOD VESSELS, or an absence of BLOOD CIRCULATION. "The number of recoverin positive cone bipolar cells transiently decreased at 6 h and 12 h after ischemia." (PMID 23776500, 2013). "The number of recoverin positive cells in the control group was 15.43±0.36, but it reduced to 13.69±0.29 at Is 6 h and 13.29±0.27 at Is 12 h after ischemia, p<0.01." (PMID 23776500, 2013). "However, the alteration patterns in recoverin immunoreactivity of the INL were slightly different from βIII-tubulin and calretinin immunoreactivities after ischemia." (PMID 23776500, 2013).
leukemia (1 paper, 2024). A malignant (clonal) hematologic disorder, involving hematopoietic stem cells and characterized by the presence of primitive or atypical myeloid or lymphoid cells in the bone marrow and the blood. "Their associated antibodies were anti-Recoverin with T cell lymphoma, multiple antibodies (anti-Yo, anti-ZIC4, anti-NMDAR) with TCC, and anti-GAD65 with leukemia." (PMID 39624101, 2024).
medulloblastoma (1 paper, 2014). A malignant, invasive embryonal neoplasm arising from the cerebellum. "Some individual members of these pathways, including GNB3, GNB5, GABRA5, RCVRN and SAG were exclusively over-expressed in Group 3 medulloblastoma." (PMID 25412507, 2014).
ocular toxoplasmosis (1 paper, 2021). Ocular toxoplasmosis is an infection in the eye caused by the parasite, Toxoplasm a gondii. "In the case of ocular toxoplasmosis, disruption of the blood-retinal barrier may cause exposure of confined retinal antigens such as recoverin." (PMID 34054794, 2021). "The severity of clinical manifestations tends to be related to the presence of anti-HSP70 and anti-recoverin autoantibodies in cases of ocular toxoplasmosis, while in patients with CNS involvement, they may have a protective role." (PMID 34054794, 2021).
Optic neuropathy (1 paper, 2024). "There is also a report of a patient with optic neuropathy associated with anti-recoverin antibodies." (PMID 39280509, 2024).
prostate tumour (1 paper, 2017). "Immunostaining of prostate tumour sections demonstrated expression of glyceraldehyde-3-phosphate dehydrogenase (GAPDH), recoverin, alpha-enolase and synaptophysin in NET cells." (PMID 28382556, 2017).
renal carcinoma (1 paper, 2020). A carcinoma arising from the epithelium of the renal parenchyma or the renal pelvis. "In recent years, with the deepening of epigenetic research, the epigenetic regulatory mechanisms of renal cancer, especially DNA methylation, are often used to predict the survival time of renal cancer, including DAB2IP, RCVRN, CRHBP, AR, and CDO1." (PMID 32733620, 2020).
systemic lupus erythematosus (1 paper, 2025). An autoimmune multi-organ disease typically associated with vasculopathy and autoantibody production. "Anti-recoverin antibodies have also been identified in patients with systemic lupus erythematosus." (PMID 40917683, 2025).
toxoplasmosis (1 paper, 2025). A parasitic disease contracted by the ingestion or fetal transmission of toxoplasma gondii. "Notably, anti-recoverin antibodies are often detected in the serum after infections such as toxoplasmosis." (PMID 40917683, 2025).
cancer (24 papers, 1996 to 2025). A tumor composed of atypical neoplastic, often pleomorphic cells that invade other tissues. "This is in an agreement with the recent study that showed the patients with RP over 50 years old with identified gene mutation and history of cancer, had serum anti-recoverin AAbs." (PMID 34926479, 2021). "Cancer-associated retinopathy patients possess recoverin-specific cytotoxic T lymphocytes (CTLs) in the peripheral blood, which can recognize aberrantly expressing recoverin in cancer cells." (PMID 29713325, 2018). "Deregulation of recoverin expression in certain types of cancer demonstrates a pathological role in cancer-associated retinopathy." (PMID 17286855, 2007). "Antibodies against recoverin have been detected in the serum of patients with cancer-associated retinopathy and are thought to penetrate the blood–retinal barrier and inhibit recoverin activity in the visual transduction cascade, causing photoreceptor degeneration." (PMID 39684616, 2024). "Anti-recoverin is one of the causes of cancer-associated retinopathy." (PMID 31694559, 2019). "The proliferation of anti-recoverin antibody-positive cancer has been slow, with a good prognosis, as recoverin itself works as a cancer antigen and induces T cell cytotoxic activity." (PMID 29362998, 2018). "SCLC cells express tumor associated antigens, which can be recognized by CTLs including, for example, the cancer/testis antigens MAGE-1 and -3, the ion channel gBK, recoverin and the neuron-associated protein Hu." (PMID 29020964, 2017). "Bilateral neuroretinitis with unilateral focal outer retinitis developed in a cancer patient positive for autoantibodies against recoverin, CRMP-5, and α-enolase." (PMID 24428923, 2014). "It has been postulated that autoimmune reactions may direct the cancer-induced anti-recoverin autoantibodies to the retina and subsequently bind recoverin in photoreceptors, triggering inflammation and cell death." (PMID 40717159, 2025). "Although anti-recoverin antibody has been considered highly correlated with cancer, systemic evaluation has disclosed no underlying malignancy in the present patient." (PMID 34122451, 2021). "It is important to remember that some anti-retinal AAbs can occur before the diagnosis of cancer, so they could be used in early cancer detection, e.g., anti-recoverin AAbs." (PMID 29713325, 2018). "Many previous studies have shown that anti-recoverin antibodies were associated with cancers in which the malignant cells expressed recoverin, and that there was not much organ-specificity regarding which type of tumors had this capability." (PMID 30271775, 2018). "This suggests that anti-recoverin AAbs were generated in response to cancer rather than to degenerating retina due to the gene mutation, because the mutations in the tumor genome can cause tumors to express mutant proteins, such as recoverin, that is normally expressed on the retina." (PMID 34926479, 2021). "However, SCLC is not the only cancer associated with anti-recoverin antibodies, which can also be found in several other cancers." (PMID 21450098, 2011). "Sera from 143 cancer patients (99 SCLC and 44 non-small cell lung cancer [NSCLC]) was tested for anti-recoverin antibodies by immunoblotting." (PMID 40416967, 2025). "We identified 12 patients with positive Abs and co-occurring cancer, most prevalent PNS antibodies included anti-GAD65, anti-Recoverin and anti-Yo." (PMID 39624101, 2024). "Anti-recoverin AAbs were also found in patients that initially presented with ocular disturbances—without cancer; however, a malignancy was later discovered." (PMID 29713325, 2018). "Anti-recoverin AAbs were also detected in patients with different cancers without visual presentation, but were not reported in healthy individuals without cancer, suggesting that AAbs are mainly generated against the cancer-expressed recoverin." (PMID 29713325, 2018).
retinopathy (22 papers, 1996 to 2025). "Retinopathy associated with anti-recoverin antibodies manifests as rapid visual impairment, night blindness, color loss, vitreous cells, and a flat or severely reduced electroretinogram (ERG)." (PMID 39280509, 2024). "For example, the clinical phenotype for anti-recoverin-associated retinopathy appears to be different from the retinopathy that is associated with anti-enolase antibodies." (PMID 29713325, 2018). "In addition to the retinopathy known to be associated with recoverin antibodies, a recent report suggested that anti-recoverin antibodies are potentially involved in late-onset ataxia." (PMID 35053759, 2021). "This approach allowed us to examine if high levels of circulating anti-recoverin antibody would produce a retinopathy." (PMID 21031137, 2010). "A rat model system has been established to elucidate the contribution of recoverin autoantibodies to the development of retinopathy." (PMID 21031137, 2010). "In some of these cases, additional antibodies were pathogenically relevant, resulting a complex clinical pictures (e.g., Recoverin antibodies and retinopathy, MOG antibodies and cerebral cortical encephalitis, and LGI1 antibodies and faciobrachial dystonic seizures)." (PMID 37025999, 2023). "Relatively little data exists showing that human CAR is dependent on induction of TH1 immunity toward recoverin, however, one report demonstrated that experimental induction of anti-recoverin CTL in mice led to protection from a recoverin-expressing tumor and simultaneous induction of retinopathy." (PMID 30271775, 2018).
tumor (14 papers, 1996 to 2025). "Although tumor pathology supports an anti-recoverin-mediated pAIR diagnosis, the other clinical features of this case do not." (PMID 38983022, 2023). "Tumour cells were immunopositive for glyceraldehyde-3-phosphate dehydrogenase, enolase and recoverin as well as neuroendocrine markers." (PMID 28382556, 2017). "In addition spleen tyrosine kinase (SYK) found to be highly expressed in RB tumors and photoreceptor protein recoverin (RCVRN) also expressed in RB were identified as RB tumor cell markers." (PMID 39695086, 2024). "In patients with presumed PR, the presence of autoantibodies can predict the presence of an underlying neoplasm (i.e., anti-recoverin autoantibodies), but their diagnostic value is not fully understood." (PMID 36769861, 2023). "An important implication of our findings that healthy individuals have an IL-10-mediated immune response toward recoverin is that expression of recoverin by malignant cells may contribute to enhanced immune regulation in the tumor microenvironment." (PMID 30271775, 2018). "However, studies suggest that CAR patients who are seropositive for anti-recoverin antibodies may have improved survival compared to those who are seronegative, possibly due to peripheral activation of recoverin-specific anti-tumor cytotoxic T-lymphocytes." (PMID 40824502, 2025).
infection (2 papers, 2021). The state of being infected such as from the introduction of a foreign agent such as serum, vaccine, antigenic substance or organism. "In summary, it seems that autoantibodies, especially against recoverin, are associated to more severity in congenitally infected patients and a milder disease in the cases with acquired form of infection." (PMID 34054794, 2021). "Compared with the control group, the signal of recoverin immunoreactivity almost disappeared in the middle region of the neural retinas after high dose infection with AAV8-HMOX1 but remained unchanged after low dose infection (panels a’)." (PMID 33691741, 2021).
Hematological cancer (1 paper, 2024). "Hematological cancer was the most frequent with the following positive antibodies: anti-Recoverin (n=2), anti-GAD65 (n=1), and anti-MA2 (n=1)." (PMID 39624101, 2024).
RCVRN also shares sentences with these, for which no sentence is quoted: Lambert-Eaton myasthenic syndrome (2 papers); Parkinsonism (2); Achalasia (1); Alzheimer disease (1); amblyopia (1); amyotrophic lateral sclerosis (1); autoimmune disease (1); autoimmune encephalitis (1); benign tumor (1); Brain atrophy (1); brain ischemia (1); Cerebral calcification (1); color vision deficiency (1); Delusion (1); encephalomyelitis (1); gynecological tumors (1); hearing loss (1); Hodgkins lymphoma (1); Huntington disease (1); Japanese encephalitis (1); lung adenocarcinoma (1); lung adenoma (1); melanoma (1); myasthenia gravis (1); myopia (1); neuroblastoma (1); neurodegenerative disease (1); neurological disorders (1); ocular infection (1); ovarian carcinoma (1).
A further 9 diseases each share a sentence with RCVRN in 1 paper.